CXCR3 (C-X-C motif chemokine receptor 3)
Diseases named in the same sentence as CXCR3 in open-access papers (continued):
Sharing a sentence is not in itself a finding about the gene and the disease.
tumor (continued). "CXCR3 is the predominant chemokine receptor mediating TE cells recruitment to tumor tissue via its ligands CXCL9 and CXCL10, and has been demonstrated to be crucial for tumor control and survival." (PMID 33466646, 2021). "CXCR3 is widely expressed by Th1 cells, CD8+ T cells and NK cells, but also by tumor cells." (PMID 34203660, 2021). "The expression of CXCL9/10/11 and CXCR3 was negatively correlated with tumor purity, indicating that they were highly expressed in infiltrating immune cells rather than tumor cells in TME." (PMID 34321012, 2021). "The levels of CXCL10 in tumor/non-tumor tissue (p = 0.0148, p = 0.0111) and TLR4 (p = 0.0343) in non-tumor tissue, but not CXCR3, were significantly higher in small-for-size graft than whole graft post-transplantation with tumor recurrence." (PMID 33990548, 2021). "Our current working hypothesis is that peripheral administration of CXCL10-Ig or CXCL9-Ig would induce the activity of CXCR3+ effector CD4+ T cells, effector CD8+ T cells, and NK cells that are then recruited to at the tumor sites to limit cancer." (PMID 34944943, 2021). "Indeed, CXCR3 signaling through interaction with CXCL9 and CXCL10 has been shown to play a relevant role in tumor homing of effector T cells." (PMID 33746981, 2021). "Notably, the CXCL9/CXCL10/CXCL11/CXCR3 axis recruits cytotoxic lymphocytes, NK cells, NKT cells, and macrophages to infiltrate tumor tissue and increases cytotoxic activity against tumor cells." (PMID 33763074, 2021). "In triple-negative BRCA, CXCL10 and CXCR3 were shown to contribute to tumor invasiveness and metastasis in spite of a high density of T cell infiltrate." (PMID 34067089, 2021). "In our model, mice treated with an antibody to block the binding of CXCL10 and CXCL11 to CXCR3 (but not the binding of CXCL9 to CXCR3) were unable to control the growth of established tumours." (PMID 33925140, 2021). "However, anti-IFN-γ significantly impaired the infiltration of CD8+CXCR3+ and CD4+CXCR3+ T cell subsets into the tumour mass." (PMID 33925140, 2021). "Additionally, the ex vivo expansion of NK cells can itself increase NK expression of CXCR3, which is further enhanced by exogenous IFN-α; thus, the process of generating NK cells for ACT increases their ability to infiltrate tumours." (PMID 34830780, 2021). "CCR5, CCR2, CXCR3, and CXCR6 were highly expressed by both tumor Tconv and Treg." (PMID 34868991, 2021). "The enrichment analysis of events that had a similar predicted splicing pattern to CXCR3 (decreased PSI in tumor), did not reveal any functions that differential CXCR3 splicing is known to affect." (PMID 34440489, 2021). "Previous studies have demonstrated that CXCR3−/− mice fail to facilitate CD8+ T cell migration without eliciting an anti-tumor immune response." (PMID 34680466, 2021). "The CXCR3/CXCL9-11 axis plays a key role in promoting the entrance of Th1 cells, CD8+T cells, and NK cells into the IME, thus producing a T cell inflammatory IME which has a strong anti-tumor effect." (PMID 35095920, 2021). "Additionally, the secretion of IFN-γ by Th1 cells can also promote CXCL9 and CXCL10 expression in the tumor microenvironment (TME) and therefore ensure the recruitment of CXCR3 expressing CD8+ T cells at tumor site." (PMID 34262562, 2021). "and CCL5 when compared to isotype-treated tumours, but had no impact on CXCR3 expression by T cell subsets." (PMID 33925140, 2021). "Finally, other approaches point to overexpressing some of the chemokine receptors involved in T cell trafficking to inflammatory sites, such as CXCR3, owing to expression of its ligands, CXCL9 and CXCL10, in the GBM tumor microenvironment (TME)." (PMID 33746981, 2021). "The reduced antitumor activities to tumor growth at a secondary site in EKO mice were likely the combined effect of diminished memory T cells due to lower IL2rb and reduced tumor trafficking due to reduced expression of CXCR3." (PMID 33553191, 2021).
tumor (continued). "We confirmed this by finding that anti-CXCR3 blocked the therapeutic effect bintrafusp alfa, resulting in tumor growth, survival, and a TME indistinguishable from nonresponders to bintrafusp alfa." (PMID 34433873, 2021). "Although binding affinity of CXCL11 to CXCR7 is low, but it can induce intracellular signaling in CXCR3-negative tumor and non-tumor cells." (PMID 34298991, 2021). "As CXCL9 and CXCL10 shares same receptor CXCR3 in T lymphocytes, we would like to understand whether the CXCL9 has similar or opposite function with CXCL10 in regulating tumour microenvironment." (PMID 31913856, 2020). "In addition, CEA-TCB treatment increased the frequency of intra-tumor CD4 and CD8 T-cells expressing CXCR3, a key receptor regulating T-cell chemotaxis." (PMID 33330050, 2020). "In line with this, CEA-TCB treatment also increased the frequency of intra-tumor CXCR3+ CD8+ and CD4+ T-cells, corroborating the relevance of the CXCL10-CXCR3 axis in mediating the attraction of T-cells leading to increase of intra-tumor T-cell infiltration upon TCB treatment (and unpublished data)." (PMID 33330050, 2020). "These are ligands for the receptors CCR5 and CXCR3, respectively, that have been shown to be over-expressed in response to IFN-γ and IL-12, and facilitate migration of activated cytotoxic T cells (CTLs) and NK cells in the tumor microenvironment." (PMID 32033490, 2020). "Tumor associated macrophages (TAMs) and myeloid suppressor cells (MDSCs) release chemokines, such as CCL17, CCL22, CCL5, CCL6 or CCL28, depending on the tumor type, to attract Tregs expressing the chemokine receptors CCR4, CCR5, CCR10 and CXCR3 from secondary lymphoid tissues to the tumor." (PMID 32937953, 2020). "Evaluation of CXCR3 expression in TILs was not possible, due to the use of collagenase necessary for tumor processing." (PMID 32461349, 2020). "Overall, our findings support a model wherein Th17 cells inhibit the expression of CXCR3 on CD8+ T cells in blood circulation by secreting IL-17A, which activates STAT3 signaling and downregulates CD8+ T cell infiltration in tumor tissues; these effects can be attenuated via Stattic." (PMID 32503584, 2020). "Similarly, for the representative values of the expression levels of genes involved in tumor-T cell interaction, we selected six genes (IFNGR1, PD-L1, CXCL9, IFNγ, PD-1, and CXCR3) and termed this group as an immune response predictor (IRP)." (PMID 32795913, 2020). "The increase in mRNA encoding expression of CXCR3, CXCL9 and CXCL10 (not CXCL11) as chemotactic chemokines suggests their involvement in the trafficking of anti‐tumor immune cells to the tumor site." (PMID 32821382, 2020). "On the one hand, the CXCR3 chemokines, especially CXCL9 and CXCL10, facilitate the recruitment of CXCR3-positive Th1, NK, and NKT cells as well as cytotoxic T lymphocytes to the tumor microenvironment, which trigger the development of a tumor-suppressive immune milieu." (PMID 31482487, 2019). "The interaction between CXCL9/CXCL10 with CXCR3 can recruit anti-tumoral dendritic cells, T lymphocytes and natural killer cells to the TME, which could be beneficial for tumor suppression." (PMID 31620367, 2019). "While cleavage and its functional consequences of CXCR3 and CX3CR1 chemokines by proteases have been rather well characterized on the biochemical level, there is hardly any in vivo data on the impact of these cleavage processes on tumor-immune interactions." (PMID 31482487, 2019). "Immunochemical analysis of primary tumor biopsies from patients demonstrated a relationship between higher type 1 IFN expression and higher intratumoral CXCL10 as well as increased numbers of CXCR3+ and granzyme B+ lymphocytes." (PMID 30899263, 2019). "CCL10–/– and CXCR3–/– mice had decreased recruitment and mobilization of Treg to HCC tumor burden." (PMID 31681327, 2019).
tumor (continued). "By performing competitive homing experiments in tumor-bearing mice, we demonstrated that Cxcr3−/− deficiency promoted increased BM infiltration for IL-15 activated but not IL12/15/18 activated Cxcr3−/− NK cells compared to the wild-type counterparts." (PMID 31699153, 2019). "Our findings further demonstrated that deletion of Camkk2 in BMDM also results in increased expression of genes encoding CXCL9 and CXCL10 chemokines that attract and activate CXCR3 expressing cells, including Th1, CD8+ T cells, and NK cells, which positively regulate anti-tumor immunity." (PMID 31164648, 2019). "The results demonstrated that polyphenols induce CXCR3 expression on regulatory T cells and increases CXCR3 ligands (CXCL9, CXCL10, CXCL11) in tumor microenvironment, it may become an important regulator in the treatment of CRC." (PMID 30973890, 2019). "However, as described for the CXCR3 system, the CX3CR1 receptor is also able to facilitate tumor cell migration and, thereby, metastasis in CX3CL1-rich tissues, e.g. the bone or the brain." (PMID 31482487, 2019). "Besides CXCR3 and CCR5 ligands, additional chemokines are now emerging as key players in the regulation of anti-tumor immunity." (PMID 30873179, 2019). "The CXCR3 and CX3CR1 chemokine receptor ligands CXCL9-11 and CX3CL1, respectively, are mainly responsible for the tumor-suppressive lymphocytic infiltration into the tumor micromilieu." (PMID 31482487, 2019). "For example, CXCL9 and CXCL10 induce effector Th1/Th17 cells and CXCL11 drives a Treg and Th2-biased effector cell polarization upon activation of CXCR3 on CD4+ T cells, while they upregulate tumor cell-related proteins that are beneficial for their survival, such as PD-L1." (PMID 31216755, 2019). "Through analysis of paired tumor and non-tumor liver samples from HCC patients, an immunosuppressive gradient has been described with increased expression of chemokine networks such as CXCR3/CXCL10 and CCR6/CCL20 which enhances macrophage and Treg recruitment to the liver." (PMID 31627733, 2019). "Cxcr3 targeting did not affect tumor growth in the spleen in the 5TGM1 and 5 T33 MM models, which is low due to NK cell surveillance." (PMID 31699153, 2019). "In addition, we have found that high expression of CXCR3 protein was closely correlated with the increased recruitment of CD4+, CD8+ tumor infiltrating lymphocytes (TILs), and dendritic cells in our previous study." (PMID 31240220, 2019). "Interestingly, mice treated with anti-LIF showed an increase in CD8+ T cell tumor infiltration and most of the infiltrating CD8+ T cells expressed the CXCL9 receptor, CXCR3." (PMID 31186412, 2019). "CXCR3 is essential for T cell recruitment into tumors and through the thymus and Th1 cells also produce IFNγ that induces additional production of CXCL9 and 10 to enhance the recruitment of cytotoxic CD8+ T cells into the tumor." (PMID 30873179, 2019). "The ligands of CXCR3 are CXC-chemokine ligand 9 (CXCL9) and CXCL10, whose elevated levels are related with enhanced amounts of tumor-infiltrating CD8+ T cells, subsequently decreased cancer metastasis and improved survival rates of colon cancer and ovarian cancer patients." (PMID 31695804, 2019). "Furthermore, this study also showed decreased expression of the lymphocyte proliferation marker CD69, the homing receptors CXCR3 and CCR5, and the NKRs NKG2D and DNAM-1 on NKT-like cells in tumor tissue compared with non-tumor tissue." (PMID 29535734, 2018). "Furthermore, although not directly tested in this study, the data support a multipronged model where DMTi-mediated upregulation of Cxcr3 chemokines enhance T cell recruitment, and MHC-I upregulation on tumor cells enhances recruited T cell activation." (PMID 29339738, 2018).
tumor (continued). "Given the non-redundant requirement of CXCR3 signaling for tumoricidal T cell trafficking to the tumor, these epigenetic modulators can enhance efficacy of combination therapy consisting of TAM/MAM blockade and checkpoint inhibitors or CTL transfer." (PMID 30483271, 2018). "We have found that high CXCR3 expression on circulating effector memory CD4+ T cells is associated with an enhancement of stage III-IV patient survival, irrespective of tumor lesion location and patient stages." (PMID 30420855, 2018). "In comparison, CXCR3 gene was not upregulated in human OC tumor subtypes and no significant changes were observed in response to estrogen in OC cells, implying a positive effect mainly associated with the CXCR7/CXCL11 axis." (PMID 30051594, 2018). "CXCR3 and its ligands influence the TME by regulating angiogenesis, recruiting activated immune cells and affecting tumor cells in divergent roles either by promoting or inhibiting tumor progression." (PMID 29707158, 2018). "Anti-programmed death receptor (Anti-PD1) therapy was not beneficial in CXCR3−/− tumor-bearing mice due to failure of efficient T cell recruitment." (PMID 30319622, 2018). "Blockade of CXCR3 on tumor cells, thus preventing metastasis, combined with increased skin expression of CXCL9/10/11 might be appropriate in circumstances where CXCR3+ effector T cells can reduce tumor growth." (PMID 30320116, 2018). "These exciting results have led us to believe that, TS-induced CXCR3 expression on CD8+Tregs contributes to dampening of the suppressive capacity of Tregs and facilitates more Teffs recruitment to tumor sites thus inducing Teffs function that reduces the tumor number and size." (PMID 29707158, 2018). "Although co-localization of monocytes/macrophages and tumor cells is necessary for engraftment, no study has systematically evaluated the role of CXCR3-expressing myeloid cells in tumor engraftment." (PMID 28358049, 2017). "Expression of tyrosinase was detected in lungs of tumor-challenged WT mice, but tyrosinase levels in CXCR3−/− mice was not different than control (no tumor challenge) mice." (PMID 28358049, 2017). "Although the requirement for tumor-expressed CXCR3 in metastatic engraftment has been demonstrated, the role of monocyte-expressed CXCR3 had not been appreciated." (PMID 28358049, 2017). "In intraabdominal metastases, tumor cells revealed a strong CXCR3 expression regardless of its expression in the corresponding primary tumor, suggesting a selection of CXCR3-overexpressing cancer cells into peritoneal niches." (PMID 28504691, 2017). "However, their increased efficacy in vivo was also found to be dependent upon secondary overexpression of CXCR3, the main receptor for the IFNγ-dependent chemokine ligands CXCL-9 and CXCL-10 found at elevated levels the TME of inflamed tumours." (PMID 29157300, 2017). "The primed CD8+ T cells acquire the ability to migrate, presumably through the up-regulation of the chemokine receptor Cxcr3 in spleen; thus these primed CD11c+ CD8+ T cells may preferentially accumulate in tumor bed." (PMID 27619885, 2016). "CXCR3, which belong to the G protein-coupled seven transmembrane family of receptors(GPCR), is involved in some signaling pathways such as PI3K and MAPK, and these pathways play a key role in tumor development." (PMID 26883105, 2016). "After 24 hr, tumour-infiltrating PKH26+ cells were recovered and stained for CXCR3." (PMID 25495686, 2015). "We observed an increased expression of CXCR3 in metastatic tumor cells compared to those from non-metastatic tumor cells." (PMID 26485767, 2015). "CXCL10/IP-10 exhibits tumor-promoting ability: CXCR3 and its ligands CXCL10/IP-10 may be involved in tumor progression and metastasis in human breast cancer cell lines." (PMID 26379707, 2015). "We thus performed a Transwell migration assay in which the 4T1 tumor cells, with or without CXCR3 KD, were tested for their migratory capability." (PMID 26485767, 2015).
tumor (continued). "Furthermore, infiltrated CXCR3+ and CCR5+ Th1 cells, a major IFN-producing cell type, were also observed in the tumor microenvironment." (PMID 26242181, 2015). "Particularly, MIG/IP-10 could chemoattract T/NK and M1 by CXCR3 expressed on activated/memory T/NK; whereas RANTES induces γδT migration to tumor sites." (PMID 26512920, 2015). "We found CXCR3 positivity in 5–35% of tumor area in 17 out of 30 patients, whilst 9 out of 30 patients had less than 5% CXCR3 positivity in tumor tissue and 4 patients showed no CXCR3 expression." (PMID 25415223, 2014). "Furthermore, we determined IP-10 and CXCR3 mRNA expression levels in 19 PDAC and 15 normal (adjacent to tumor tissues) pancreatic tissue samples by qPCR." (PMID 25415223, 2014). "Moreover, besides CXCL11, CXCR3 is also bound by CXCL9 and CXCL10 to promote tumor growth, metastasis, angiogenesis and immune cell infiltration into tumors." (PMID 24904289, 2014). "The higher number of circulating CXCR3+ Tregs in PDAC patients may result from stromal induction of IP-10 and may also result in a higher number of infiltrating Tregs in the tumor." (PMID 25415223, 2014). "The tumor cells were negative for CXCR3 by FACS and reverse transcriptase real-time PCR (data not shown)." (PMID 24023642, 2013). "Flow cytometry analyses showed that CXCR3, mainly expressed by Th1 cells and CTL, was present on significantly fewer CD4+ and CD8+ LPL (p<0.01) in the tumor tissue compared to the unaffected tissue, whereas in the case of Treg there was only a trend towards decreasing frequencies of CXCR3+ cells." (PMID 22319577, 2012). "In addition, we analyzed CXCR3 and CXCL9 expression in neu-expressing tumors on days 3 and 5 after adoptive transfer into tumor-bearing neu-N mice." (PMID 22359647, 2012). "Blocking of chemokine receptor CCR2 but not CCR1, CCR3, CCR5, CCR7 or CXCR3 on CTL007 with Abs significantly inhibited tumor cell apoptosis." (PMID 21450101, 2011). "Recently, we have shown in an organotypic culture system (reconstruct) that migration of CTL derived from a CRC patient towards autologous tumor cells was mediated by chemokine receptor CXCR3 expressed by the T cells, and CXCL11 chemokine secreted by the autologous tumor cells." (PMID 21450101, 2011). "The notable exception of this trend was observed in COAD, READ, and STAD, where CXCR3 displayed a positive correlation with PEBP1/STK11 expression, highlighting the complex and context-dependent interplay between PEBP1/STK11 and chemokine-mediated immune regulation in the tumor microenvironment." (PMID 40806276, 2025). "Moreover, it reconciles why high intra-tumoral CXCR3 expression correlates with favorable prognosis: in the absence of a dominant systemic decoy, high local CXCR3 signifies a well-infiltrated, immune-hot OS capable of mounting an effective anti-tumor response." (PMID 41516196, 2025). "Thus, the role of CXCL9/CXCR3 in HCC is complex, suggesting that its therapeutic potential may depend on the specific tumor context or setting." (PMID 40145607, 2025). "A CXCR3/CXCL9/CXCL10 axis could drive T cell infiltration into KPCY55 tumors of GPR55 KO mice, suggesting that GPR55 suppresses this pathway in PDAC, thereby promoting tumor growth." (PMID 39885986, 2024). "We, then, demonstrated that the selected tumor cells did not express CXCR3." (PMID 38953994, 2024). "CXCR3 expression remained markedly lower in the CX3CR1+ subset than in the CX3CR1− subset of Pmel-1 T cells in the spleen, suggesting that peripheral CX3CR1+ Pmel-1 T cells have a decreased capacity to migrate to the tumor microenvironment via the CXCR3-CXCL9/CXCL10 axis." (PMID 38881188, 2024). "Likewise, the adoptive transfer of CXCR3+ CD8+ T cells into CXCR3KO mice enabled response to CXCL10-Fc, showing that the direct effect on CD8+ T cells induced by CXCL10-Fc is sufficient to restrain tumor growth." (PMID 39474427, 2024).